ADAMTSL1 (ADAMTS like 1)
Synonyms: ADAMTSL-1; ADAMTSR1; C9orf94; FLJ35283; PUNCTIN
Tractability: Antibody: UniProt places it where antibodies can reach, with high confidence; UniProt predicts a signal peptide or a membrane-spanning region; its Gene Ontology location is reachable by antibodies, with medium confidence.
Gene: Protein-coding gene on chromosome 9 (17,906,563 to 18,910,950, forward strand). Ensembl gene ENSG00000178031.
Subcellular location: Secreted, extracellular space, extracellular matrix
Subcellular location (Human Protein Atlas): Vesicles; Predicted to be secreted
Pathways (Reactome):
Disease: Defective B3GALTL causes PpS
Metabolism of proteins: O-glycosylation of TSR domain-containing proteins
Gene Ontology:
Biological process: extracellular matrix organization
Cellular component: endoplasmic reticulum lumen
Genetic constraint (gnomAD): Loss-of-function variants: 121 observed, 189.06 expected, observed/expected ratio (o/e) 0.64, 90% interval 0.55 to 0.74. The synonymous counts are far from expectation, so gnomAD's model fits this gene poorly and the ratio says little. Missense variants: 2,647 observed, 2,285.4 expected, observed/expected ratio (o/e) 1.16, 90% interval 1.12 to 1.2. Synonymous variants: 1,113 observed, 909.68 expected, observed/expected ratio (o/e) 1.22, 90% interval 1.16 to 1.29.
Homologues: Orthologues: chimpanzee ADAMTSL1 (99% identical), macaque ADAMTSL1 (98% identical), rabbit ADAMTSL1 (94% identical), dog ADAMTSL1 (94% identical), pig ADAMTSL1 (93% identical), rat Adamtsl1 (91% identical), mouse Adamtsl1 (91% identical), guinea pig ADAMTSL1 (89% identical), tropical clawed frog adamtsl1 (69% identical). Paralogues in human: ADAMTSL3 (43% identical), ADAMTS7 (15% identical), ADAMTS12 (15% identical), ADAMTS20 (14% identical), ADAMTS9 (14% identical), ADAMTS16 (12% identical), ADAMTS18 (12% identical), THSD4 (12% identical), ADAMTSL4 (12% identical), PAPLN (12% identical), ADAMTS13 (12% identical), ADAMTS6 (12% identical), and 13 more.
Diseases named in the same sentence as ADAMTSL1 in open-access papers:
ADAMTSL1 is named in the same sentence as 21 diseases in open-access papers, as found by Europe PMC text mining. Sharing a sentence is not in itself a finding about the gene and the disease. The quoted sentences say what the papers report.
breast carcinoma (5 papers, 2017 to 2021). "Very few information about ADAMTSL1, 2 and 4 is available in cancers, however two SNPs in ADAMTSL1 gene were associated with early-onset disease-free survival in breast cancers and ADAMTSL1 was shown to regulate chondrosarcoma cell proliferation." (PMID 33805340, 2021). "Several genes related to ADAMTSL1 have been implicated in the development of normal breast tissue and in the initiation and progression of breast cancer including ADAMTS126, ADAM1027, ADAM1228 and ADAM1729." (PMID 29158497, 2017). "Here, the authors conduct a meta-analysis to explore genetic variance linked to breast cancer in young women, identifying a prognostic association with germline variation of ADAMTSL1." (PMID 29158497, 2017). "ADAMTSL1 was reported to be associated with prognosis of breast cancers in young women." (PMID 33680913, 2020). "UBAP1 has also been reported fused, in-frame, with UBAP2 in one breast cancer tumor, with ADAMTSL1 in one low grade glioma." (PMID 28423358, 2017). "We have also discussed the possible impact of these variants on the methylation of ADAMTSL1, its interaction with other members of the ADAMTS gene family and their association with the expression of other biologically relevant genes such as AREG in the context of breast cancer prognosis." (PMID 29158497, 2017).
glioma (3 papers, 2017 to 2024). A benign or malignant brain and spinal cord tumor that arises from glial cells (astrocytes, oligodendrocytes, ependymal cells). "ADAMTSL1 is involved in promoting the progression of gliomas and is a potential prognostic biomarker for malignant invasion in glioma." (PMID 39200124, 2024). "Furthermore, the mutations of ADAM family members were assessed in gliomas, and ADAMTS20, ADAMTSL1 (ADAMTS-like protein 1), and ADAMTSL9 mutation probability was as high as 3%; other ADAM family members also had a series of mutations that were mainly concentrated in amplification." (PMID 36172139, 2022).
glaucoma (2 papers, 2021 to 2025). Increased pressure in the eyeball due to obstruction of the outflow of aqueous humor. "Moreover, ADAMTSL1 caused the dislocation of microspherophakic lens that causes severe myopia, glaucoma, or cataract." (PMID 34222226, 2021). "A mutation in Trp42 to Arg in ADAMTSL1 has been identified in glaucoma patients, and this variant did not facilitate its secretion." (PMID 40878842, 2025).
myopia (2 papers, 2021). "A C-mannosylation-defective mutation of ADAMTSL1 was identified as the first disease-associated variant affecting the C-mannosylation of the W-x-x-W motif, which caused various phenotypes including developmental glaucoma, myopia, and retinal defects." (PMID 34500691, 2021).
abdominal aortic aneurysm (1 paper, 2024). Enlargement and ballooning of the vessel that supplies arterial blood to the abdomen, pelvis and legs. "Indeed, ADAMTSL1 variants are enriched in intracranial aneurysms, and ADAMTSL1 is downregulated in abdominal aortic aneurysms." (PMID 38324186, 2024).
Allergy (1 paper, 2017). An allergy is an immune response or reaction to substances that are usually not harmful. "However, nonsynonymous mutations were identified in the coding sequences of Cer1, Ttc39b, Ccdc171, Cntln, Adamtsl1, Haus6, Gm12551, and Dennd4c, but these genes do not have any prior documented associations with allergy, IgE, or asthma." (PMID 28696925, 2017).
heart failure (1 paper, 2024). Inability of the heart to pump blood at an adequate rate to meet tissue metabolic requirements. "ADAMTSL1 expression increases in hearts of mice with experimental heart failure and fibrosis, linking ADAMTSL1 to cardiac ECM remodeling." (PMID 38324186, 2024).
hypospadias (1 paper, 2022). Hypospadias is the displacement of the urethral meatus on the ventrum of the penis. "Additionally, investigation of cases with hypospadias and variants in genes enriched in multiple tissues (e.g., ADAMTSL1, BDNF) may potentially lead to the identification of new syndromes, or the expansion of phenotypes for existing syndromes." (PMID 35457073, 2022).
lymphedema (1 paper, 2023). Excess fluid collection in tissues, causing swelling. "Lymphedema samples exhibited aberrant expression of metalloproteinases such as ADAMTSL1 and a decrease in transcripts associated with adipocyte identity (FABP4, CD36)." (PMID 38131378, 2023).
ovarian carcinoma (1 paper, 2016). A malignant neoplasm originating from the surface ovarian epithelium. "We thus examined ADAMTSL1 gene expression in ovarian cancer cell lines in an adherent and sphere condition, but the expression was not detectable (data not shown)." (PMID 27072580, 2016).
tumor (7 papers, 2016 to 2025). "Of those, eight (HOXA3, HOXA5, ATP10A, SOX2, MIR922, ADAMTSL1, KHDRBS2, and LITD1) were hypermethylated in at least one LS tumor group like here in FAP normal, whereas NEDD4L, and FOXP1 were hypermethylated in LS carcinomas and here in LS normal." (PMID 40753397, 2025). "Overexpressed in tumor matrix were proteins involved in ECM organization such as LOX, LAMB3, ADAMTSL1 and FBN2." (PMID 35340765, 2022).
ADAMTSL1 also shares sentences with these, for which no sentence is quoted: cancer (3 papers); asthma (1); chondrosarcoma (1); colon tumor (1); colorectal cancer (1); congenital glaucoma (1); intracranial aneurysms (1); melanoma (1); neuromuscular disease (1); retinal (1).